LRFN3 (leucine rich repeat and fibronectin type III domain containing 3)
Description:
Cell adhesion molecule that mediates homophilic cell-cell adhesion in a Ca(2+)-independent manner. Promotes neurite outgrowth in hippocampal neurons (By similarity).
Synonyms: SALM4; MGC2656; FIGLER1
Tractability: Antibody: its Gene Ontology location is reachable by antibodies, with high confidence; UniProt places it where antibodies can reach, with medium confidence; UniProt predicts a signal peptide or a membrane-spanning region. PROTAC: its protein half-life has been measured.
Gene: Protein-coding gene on chromosome 19 (35,935,358 to 35,946,624, forward strand). Ensembl gene ENSG00000126243.
Subcellular location: Cell membrane; Cell projection, axon; Cell projection, dendrite; Synapse; Presynaptic cell membrane; Postsynaptic cell membrane
Pathways (Reactome):
Neuronal System: Synaptic adhesion-like molecules
Gene Ontology:
Biological process: regulation of presynapse assembly; regulation of synaptic membrane adhesion; synaptic membrane adhesion
Cellular component: cell surface; plasma membrane; presynaptic active zone membrane; axon; dendrite; glutamatergic synapse; postsynaptic density membrane; postsynaptic membrane; postsynaptic specialization membrane; presynaptic membrane; synapse
Genetic constraint (gnomAD): Loss-of-function variants: 11 observed, 16.52 expected, observed/expected ratio (o/e) 0.67, 90% interval 0.42 to 1.1. The upper end of that interval is the gene's LOEUF score, 1.1, which puts it in group 4 of 6, group 1 being the genes least tolerant of losing a copy. Missense variants: 736 observed, 834.36 expected, observed/expected ratio (o/e) 0.88, 90% interval 0.83 to 0.94. Synonymous variants: 450 observed, 405.21 expected, observed/expected ratio (o/e) 1.11, 90% interval 1.03 to 1.2.
Homologues: Orthologues: chimpanzee LRFN3 (99% identical), macaque LRFN3 (99% identical), dog LRFN3 (97% identical), pig LRFN3 (97% identical), guinea pig LRFN3 (97% identical), rat Lrfn3 (96% identical), mouse Lrfn3 (96% identical), zebrafish zgc:172282 (55% identical), tropical clawed frog lrfn1.2 (53% identical). Paralogues in human: LRFN1 (54% identical), LRFN4 (51% identical), LRFN2 (50% identical), LRFN5 (50% identical), SLIT3 (24% identical), LRRN2 (23% identical), SLIT1 (23% identical), SLIT2 (23% identical), TLR9 (21% identical), LRRN1 (21% identical), LINGO1 (21% identical), LRRN3 (21% identical), and 13 more.
Diseases named in the same sentence as LRFN3 in open-access papers:
LRFN3 is named in the same sentence as 7 diseases in open-access papers, as found by Europe PMC text mining. Sharing a sentence is not in itself a finding about the gene and the disease. The quoted sentences say what the papers report.
Anxiety (1 paper, 2021). Intense feelings of nervousness, tension, or panic often arise in response to interpersonal stresses. "In addition, Lrfn3−/− mice showed no changes in tests measuring locomotion, motor learning, social interaction, sensory-motor coordination, repetitive behaviors, anxiety-like behavior, or depression-like behavior." (PMID 34588597, 2021).
glioblastoma (1 paper, 2015). The most malignant astrocytic tumor (WHO grade IV). "Two mRNAs whose expression characterizes LTCs vs LTPs, LRFN3 (encoding for Leucine Rich repeat and Fibronectin type III domain containing 3) and NR2F6 (Nuclear Receptor subfamily 2 group F member 6), were previously included in the “classical” signature of glioblastoma." (PMID 26188123, 2015).
posttraumatic stress disorders (1 paper, 2021). "Treatment of Lrfn3−/− mice with fluoxetine, a medication used to treat excessive fear memory in humans such as posttraumatic stress disorders (PTSDs), which directly inhibit GluN2B-containing NMDARs (GluN2B-NMDARs), improved NMDAR-mediated currents and fear memory consolidation in Lrfn3−/− mice." (PMID 34588597, 2021).
LRFN3 also shares sentences with these, for which no sentence is quoted: autism (2 papers); depression (1); HCMV infection (1); schizophrenia (1).